CRP (C-reactive protein)
Diseases named in the same sentence as CRP in open-access papers (continued):
Sharing a sentence is not in itself a finding about the gene and the disease.
myocardial infarction (continued). "While in rats CRP-mediated complement activation seems to contribute to myocardial damage and while inhibition of CRP by a CRP-cross-linker may be protective, complement inhibition in human myocardial infarction has never been conclusively demonstrated to be beneficial." (PMID 24799767, 2014). "In contrast to the CRP axis, VCAM and tPA related both to death and to recurrent nonfatal acute coronary syndromes of myocardial infarction or unstable angina." (PMID 23525424, 2013). "The identified significant predictors included no-reflow, thrombolysis in myocardial infarction (TIMI) grading, mean platelet volume and lymphocyte ratio (MPVLR), neutrophil to lymphocyte ratio (NLR), and levels of hypersensitive C-reactive protein (hs-CRP) and brain natriuretic peptide (BNP)." (PMID 41451020, 2025). "In a large cohort of patients with myocardial infarction, with ST elevation, PTX3 but not the liver-derived short pentraxin CRP or other cardiac biomarkers (NT-proBNP, TnT, CK) predicted 3-month mortality after adjustment for major risk factors and other acute-phase prognostic markers." (PMID 23690668, 2013). "Elevated WBC and CRP levels are independent predictors of development of left ventricular systolic dysfunction after an ACS, regardless of several confounders including diagnosis of myocardial infarction." (PMID 19503842, 2009). "CRP is the most examined inflammation marker in relation to cardiovascular disease (CVD) and substantial evidence indicates that baseline hsCRP level is an independent predictor of cardiovascular events both in patients with non-fatal myocardial infarction (MI) and in apparently healthy individuals." (PMID 21152016, 2010).
Hypoalbuminemia (701 papers, 2003 to 2026). The concentration of albumin in the blood circulation is below the lower limit of normal. "Hypoalbuminemia was also associated with preoperative biliary drainage (p < 0.001), the preoperative bilirubin level (p < 0.001), the preoperative CRP level (p < 0.001) and an increased CA19-9 (p < 0.001)." (PMID 41504962, 2026). "Respondents described improved outcomes after nutritional optimization in cases with hypoalbuminemia, while others underlined the role of CRP or glycated hemoglobin (HbA1c) when infection risk or glycemic control were concerns." (PMID 41227080, 2025). "For instance, AKI, CRP, and hypoalbuminemia have been consistently associated with poor outcomes in liver-related complications and infections, including SBP, due to reduced immune defense." (PMID 41353185, 2025). "According to this study, individuals with inflammation or disease burden had fever, high CRP, hypoalbuminemia, and severe infections; these symptoms are linked to reduced HDL-C values." (PMID 40607030, 2025). "PIV also correlates with CRP and hypoalbuminemia—features of the CRP/albumin ratio—previously linked to increased osteoporosis risk." (PMID 41140653, 2025). "Other studies found that a higher level of CRP, hypoalbuminemia, and hypocomplementemia are linked to a more severe clinical presentation and a more severe APSGN." (PMID 41246678, 2025). "Factors associated with mortality included elevated CRP levels (OR: 1.01; p = 0.003), increased creatinine (OR: 1.42; p = 0.028), hypoalbuminaemia (OR: 0.24; p = 0.046), renal involvement (OR: 2.86; p = 0.031), and pulmonary involvement (OR: 3.21; p = 0.003)." (PMID 40564119, 2025). "For instance, systemic inflammatory response markers such as plasma C-reactive protein (CRP), hypoalbuminemia, and absolute white cell count (WBC) are associated with cancer development and progression." (PMID 41516970, 2025). "Hypokalaemia (2.6 mEq/l), hypomagnesaemia (1.25 mg/dl) and hyponatraemia (128 mEq/l) were associated with hypoalbuminaemia (2.1 g/dl), C-reactive protein (CRP) 27.1 mg/l (N < 5) and stool molecular-panel detected enteropathogenic Escherichia coli." (PMID 40088929, 2025). "Inflammation-related biomarkers, such as albumin and C-reactive protein (CRP), have been identified as prognostic indicators in RCC, with hypoalbuminemia and elevated CRP levels consistently associated with poor clinical outcomes." (PMID 40836295, 2025). "Neuromuscular patients and patients with dysphagia face higher complication risk but lower short-term mortality, while hypoalbuminemia, elevated CRP, and high NRS-2002 or declining PNI identify patients at greater risk of death." (PMID 41303753, 2025). "Nutritional risk, nausea and vomiting, constipation, pancreatic insufficiency, severe infection, chronic kidney disease, fever, high CRP, hypoalbuminemia, and receiving parenteral nutrition are associated with lower HDL-C levels in patients." (PMID 40607030, 2025). "In animal models, high-phosphate diets (1.2%) increase TNF-α, IL-6, and C-reactive protein (CRP) and lead to weight loss, hypoalbuminemia, and muscle atrophy." (PMID 41516280, 2025). "Our research confirmed the association of severe infections, fever, high CRP, and hypoalbuminemia with lower HDL-C levels." (PMID 40607030, 2025). "Both studies included patients with mixed solid tumors in the pre-treatment phase and found GPS 2 (elevated CRP and hypoalbuminemia) to be significantly associated with deficit accumulation frailty (Balducci criteria and Edmonton Frailty Scale)." (PMID 37213604, 2023). "Research shows that hypoalbuminaemia, hyponatraemia and an elevated CRP have been identified as independent risk factors for mortality." (PMID 37730573, 2023). "Hypoalbuminemia, increased CRP, D-dimers, LDH and PCT, were associated with severe disease with threshold values of 38.85 g/L, 33.55 mg/L, 0.635 μg/L, 263.5 μg/L and 0.065 ng/mL respectively." (PMID 37189760, 2023).
Hypoalbuminemia (continued). "Many patients suffered from advanced diseases with inflammatory components (elevated CRP in 36% and hypoalbuminemia in 21%), which contribute to cachexia-related muscle loss (such as in pancreatic cancer)." (PMID 37444508, 2023). "While CRP is a pro-inflammatory molecule, hypoalbuminemia reflects poor nutritional status associated with increased mortality in patients with cancer." (PMID 37213604, 2023). "Hypertriglyceridemia and hypoalbuminemia, together with C-reactive protein, are probably metabolic factors associated to systemic inflammation and not only to poor or altered metabolic and nutritional status." (PMID 37693244, 2023). "Inflammation during the acute ICU phase is usually associated with elevated CRP levels and hypoalbuminemia." (PMID 37299429, 2023). "Hypoalbuminemia is associated with a higher risk of nutritional impairment, lower overall survival and higher inflammatory markers (e.g., CRP) since inflammation and malnutrition decrease albumin concentration by reducing albumin synthesis." (PMID 36145174, 2022). "We found that concomitant high hs-CRP levels (> 3 mg/L) and hypoalbuminemia (< 35 g/L) increased the risk of long-term all-cause mortality among CAD patients near four-fold." (PMID 34961476, 2021). "Our study indicated that, especially for CAD patients with high hs-CRP levels, hypoalbuminemia increased the risk of long-term all-cause mortality." (PMID 34961476, 2021). "Major risk factors include preoperative C-reactive protein (p = 0.001), hypoalbuminemia (p = 0.011), history of total joint replacement (p < 0.001), duration of preoperative antibiotics treatment (p = 0.038) and psoas muscle abscess (p < 0.001)." (PMID 34830626, 2021). "When hs-CRP and albumin were combined, CAD patients with high hs-CRP levels (> 3 mg/L) and with hypoalbuminemia were at the highest risk of death compared with their reference group (hs-CRP ≤ 3 mg/L and albumin > 35 g/L; HR 3.79; 95% CI 1.91–7.52)." (PMID 34961476, 2021). "Clinically, prospective large scale population studies are necessary to more deeply explore high hs-CRP levels and hypoalbuminemia in CAD patients with a high risk of mortality." (PMID 34961476, 2021). "Our study evaluated 5 risk factors as significant major findings: hypoalbuminemia (<3.4 g/dL), higher preoperative CRP (>130 mg/L), psoas muscle abscess, longer preoperative antibiotics treatment (>8 days) and history of total joint replacement." (PMID 34830626, 2021). "We systematically assessed the significance of concomitant high hs-CRP levels and hypoalbuminemia on long-term all-cause mortality among CAD patients." (PMID 34961476, 2021). "Other factors that influenced the risk of postoperative infections were high levels of CRP, hypoalbuminaemia, and the requirement of laparotomy." (PMID 34640421, 2021). "The multivariate analysis revealed that underlying DM, hypoalbuminemia, high baseline hs-CRP and PCT levels, and large maximal diameter of abscess were independent factors associated with prolonged hospital stay." (PMID 33573593, 2021). "The present study showed that the maximal diameter of the abscess, underlying DM, hypoalbuminemia, and high hs-CRP and PCT levels were independent factors related to prolonged hospitalization." (PMID 33573593, 2021). "This study systematically examined the significance of concomitant hypoalbuminemia and high hs-CRP levels on long-term all-cause mortality among CAD patients." (PMID 34961476, 2021). "ECOG PS 2–4 (p < 0.001), former or current smoker (p = 0.021), advanced T (p = 0.022), N (p = 0.010), and M (p = 0.041) stages, high CRP (p = 0.002), and hypoalbuminemia (p = 0.019) were associated with a shorter OS." (PMID 34943437, 2021). "Our results confirmed low TIBC (< 200 μg/dL) was associated with hypoalbuminemia and high C-reactive protein." (PMID 33863963, 2021).
Hypoalbuminemia (continued). "Our study evaluated five risk factors as significant major findings: hypoalbuminemia (<3.4 g/dL), higher preoperative CRP (>130 mg/L), psoas muscle abscess, longer preoperative antibiotics treatment (>8 days) and history of total joint replacement." (PMID 34830626, 2021). "In fact, in the present study, elevated β2MG was also associated with not only hyperphosphatemia, but also hypoalbuminemia and high CRP levels before starting HD." (PMID 33019590, 2020). "Some studies have suggested sarcopenia is associated with higher levels of CRP and hypoalbuminemia, which were shown to be prognostic factors for RCC." (PMID 32213202, 2020). "Our results revealed that a low LMR was significantly associated with older age, hypoalbuminemia, a high serum CRP level, and male sex in patients with early‐stage gastrointestinal cancers." (PMID 33005853, 2020). "Hypoalbuminemia and C-reactive protein (CRP) are associated with AVF thrombosis indirectly and directly." (PMID 30769951, 2019). "Few studies have shown that hypoalbuminemia strongly associates with increased CRP and/or IL-6 levels in CKD patients, while data on the association of BMI with inflammation within these clinical settings is still contradictory." (PMID 31316299, 2019). "In multivariable analysis, independent associates of hypoalbuminemia were higher CRP at baseline, pulmonary oedema on chest X-ray, history of heart failure with reduced ejection fraction, older age and calcium channel blocker use prior to admission." (PMID 31095609, 2019). "Some studies showed that capsule endoscopy in patients with the additional symptoms or signs, such as weight loss, increased the erythrocyte sedimentation rate, increased C-reactive protein level, and hypoalbuminemia, had a higher diagnostic yield." (PMID 31205466, 2019). "CRP > 6 mg/L (aOR: 8.96), hypoalbuminemia (aOR: 6.50) and KT/V < 1.2 (aOR: 3.70) were associated with the lack of seroconversion." (PMID 33708291, 2019). "The positive rates of CE findings were significantly higher in CAP patients associated with diarrhea, weight loss, elevated ESR, hypoalbuminemia, or increased C-reactive protein (CRP), P < .05." (PMID 29465542, 2018). "The main finding of this study is that age < 65 years, IRVS, hypoalbuminemia, and elevated CRP levels were identified as risk factors for pneumococcal bacteremia in patients with pneumococcal CAP." (PMID 29382316, 2018). "The coronary severity during the acute KD phase (before IVIG treatment) was associated with IVIG responsiveness, hypoalbuminemia, and C-reactive protein (CRP) levels." (PMID 28587647, 2017). "Given that hypoalbuminemia and CRP are associated with poor prognosis in cancer patients, we also evaluated the potential prognostic role of the GPS on long-term outcome in patients undergoing definitive CRT for LAESCC." (PMID 28717855, 2017). "Coadministration of glucocorticoid and inflammation, reflected by elevated CRP level and hypoalbuminemia, are associated with voriconazole clearance." (PMID 27096102, 2016). "GPS 1 group had a significantly prolonged OS compared with GPS 2 group, indicating an increased risk of patients with both elevated CRP and hypoalbuminemia." (PMID 27104127, 2016). "Elevated CRP level, representing an inflammation cause of the host, would be more likely represent an inflammation cause for fGGOs, instead of hypoalbuminemia, representing malnutrition of the host." (PMID 26752624, 2016). "But after adding GI symptom score, CRP and 24-hour urine albumin excretion into the fully adjusted model, the association between lower eGFR and lower serum albumin/higher risk of hypoalbuminemia was basically abolished." (PMID 26651991, 2015). "To examine how much GI symptoms and inflammation mediated the association between lower eGFR and hypoalbuminemia, we simultaneously controlled for GI symptoms and CRP in a model with eGFR as the exposure and serum albumin as the outcome." (PMID 26651991, 2015).
Hypoalbuminemia (continued). "In our cohort, we detected a marked increase in the capillary leak index due to hypoalbuminaemia and high CRP levels, most probably caused by a systemic inflammatory reaction after surgery." (PMID 25360698, 2014). "We defined CLI as a parameter of capillary leak, assuming that increased vascular permeability caused by systemic inflammation is associated with high CRP levels and hypoalbuminemia." (PMID 22873410, 2012). "The indeterminate QFT results in the inpatient group were independently associated with lymphocytopenia, hypoalbuminemia, and high C-reactive protein levels." (PMID 21513568, 2011). "A study found that a combination of an elevated CRP and hypoalbuminaemia (GPS) was significantly associated with overall and cancer specific survival in colorectal cancer." (PMID 21176210, 2010). "High levels of serum CRP are associated with hypoalbuminemia, which may be due to decreased hepatic capacity to synthesize albumin as a result of increased expression of a range of inflammatory factors." (PMID 40309739, 2025). "Interestingly, elevated basal CRP and hypoalbuminemia were also associated with a worse prognosis and higher in-hospital and 3-month mortality." (PMID 38611643, 2024). "All three macaques (C-1, C-2, C-3) showed disease features including anorexia, lethargy, central nervous system anomalies, leukopoenia, thrombocytopenia, hypoalbuminemia, and elevations in circulating levels of liver-associated enzymes and C-reactive protein consistent with previous LF studies." (PMID 38164768, 2024). "Furthermore, systemic inflammatory markers like C-reactive protein, interleukin-1, and the tumor necrosis factor are intricately linked with hypoalbuminemia due to their role in inhibiting albumin synthesis." (PMID 38473396, 2024). "Risk factors associated with post-PEG prognosis may include hypoalbuminemia, a history of aspiration pneumonia, and elevated C-reactive protein levels." (PMID 37240466, 2023). "In addition to CRP, hypoalbuminemia was extracted as an independent risk factor for PFS in our study." (PMID 37073452, 2023). "The variables of age, gender, KPS, CCI, BMI, CRP, tumor size, pathological T-stage, nuclear grade, and lymphovascular invasion demonstrated significant associations within an integrated model considering both sarcopenia and hypoalbuminemia." (PMID 37371699, 2023). "Other risk factors were hypoalbuminemia, hypoproteinemia, and CRP elevation." (PMID 36291494, 2022). "Our study suggests that hypoalbuminemia should be treated before surgery, and some risk factors that may lead to elevated C-reactive protein should be actively treated, such as infection, thrombosis and other diseases." (PMID 36684183, 2022). "Hence, higher mGPS, meaning hypoalbuminemia and elevated CRP levels, is associated with a poor prognosis in patients with NSCLC, which is consistent with our conclusion." (PMID 35619963, 2022). "Moreover, the laboratory test performed on the 3rd day of admission showed an increase of the CRP value (216.65 mg/L), and the persistence of elevated NT-proBNP (9,884.2 pg/mL) and D-dimer (1,198 ng/mL), associating also hypoalbuminemia (2.45 g/dL)." (PMID 36474612, 2022). "In a multivariate logistic regression model, severe hypoalbuminemia increased the risk of in-hospital mortality (OR 2.18 95% CI 1.03–4.62; p = 0.039) after adjusting by age, gender, inflammation markers (C-Reactive protein), comorbidities and severity of the episode measured by MEWS score." (PMID 34768653, 2021). "Importantly, hypoalbuminemia and elevated CRP are not only associated with poor outcomes in several cancer types, but also to osteoporosis and fracture risk." (PMID 34182958, 2021). "Hypoalbuminemia is a feature of acute and chronic inflammation, as depicted by the inverse association with hs-CRP, and might favor thrombosis at the site of vascular lesion as albumin encompasses anticoagulant and antiplatelet properties." (PMID 34218413, 2021).